RNF20 (ring finger protein 20)
Diseases named in the same sentence as RNF20 in open-access papers (continued):
Sharing a sentence is not in itself a finding about the gene and the disease.
vitamin D deficiency (1 paper, 2021). A nutritional condition produced by a deficiency of VITAMIN D in the diet, insufficient production of vitamin D in the skin, inadequate absorption of vitamin D from the diet, or abnormal conversion of vitamin D to its bioactive metabolites. "However, the observation that neither Rnf20/40-deficient mice, nor patients with low expression of RNF20/40-dependent genes displayed vitamin D deficiency suggests that vitamin D supplementation alone would likely not be sufficient to compensate for decreased vitamin D receptor levels." (PMID 34088983, 2021).
tumor (39 papers, 2011 to 2025). "To further investigate the role of RNF20 loss in tumor growth and metastatic dissemination in vivo, we injected control and RNF20 + /- A549 cells subcutaneously and intravenously into nude mice." (PMID 40436847, 2025). "RNF20/40 acts as a tumor suppressor and its loss-of-function and decreased activity have been associated with tumor progression, invasiveness and epithelial to mesenchymal transition (EMT)." (PMID 35408843, 2022). "In some cancers, H2Bub1 loss by way of loss of RNF20 has been implicated in an early inflammatory response, while in others it has been linked to progression of the tumour and in some cases, a worse prognosis." (PMID 33233707, 2020). "In line with a tumour suppressive function, copy number loss of RNF20 has been reported in HGSOC and pre-invasive dysplastic airway lesions." (PMID 33233707, 2020). "Monoubiquitination of histone 2B (H2Bub1) by the heterodimeric ubiquitin ligase complex RNF20/RNF40 has been described to have tumor suppressor functions and loss of H2Bub1 has been associated with cancer progression." (PMID 33070155, 2020). "Lastly, in a study of clear cell renal cell carcinoma, loss of RNF20 detected in primary tumours by immunohistochemistry was a marker of poor prognosis." (PMID 30669413, 2019). "The E3 ligase RNF20 functions as a tumor suppressor and reduction in RNF20 levels causes defective HR and genome instability." (PMID 30304473, 2018). "RNF20 is a tumor suppressor linked to several types of cancers." (PMID 37230987, 2023). "Interestingly the HPV viral protein L2 interacts with RNF20/40, and this interaction phenocopies the loss-of-function effects, promoting tumor growth and EMT." (PMID 35408843, 2022). "In the same tumour cohort, complete loss of RNF20 assessed using immunohistochemical staining was seen in only 6% of tumours (26 of 424) and did not correlate with loss of H2Bub1, implying that abrogation of RNF20 function does not explain the majority of H2Bub1 loss present in these tumours." (PMID 33233707, 2020). "The importance of the RNF20/40-Eg5 pathway in spindle assembly suggests that RNF20/40 and Eg5 could be implicated in the rapid growth of tumour cells." (PMID 27557628, 2016). "In line with our previous findings, a gap closure assay and Boyden chamber assay revealed that the loss of RNF20 and RNF40 both impaired tumor cell migration." (PMID 40597205, 2025). "Taken together, these data suggest a critical role of HIF1α-mediated metabolic rewiring in the increased tumor growth and metastasis upon RNF20 LOF in vivo." (PMID 40436847, 2025). "Taken together, high RNF20 and RNF40 levels are associated with poor patient survival and play a tumor-supportive role in CC." (PMID 40597205, 2025). "Tumor volume in mice transplanted with RNF20 + /- A549 cells was already larger 9 days post-injection and continued to increase thereafter." (PMID 40436847, 2025). "Here, we provide evidence that the evolutionarily conserved ubiquitin ligase Bre1 and its human homolog RNF20, a tumor suppressor, function as HR mediator proteins to regulate recombination in an E3 ligase-independent manner." (PMID 37230987, 2023). "Recent reports suggested a tumor-suppressive role of H2Bub1 and the RNF20/RNF40 complex in different cancer entities." (PMID 37770435, 2023). "Cell division cycle 73 (CDC73), which is a member of the PAF1 complex, is another tumor suppressor that directly interacts with RNF20/40 and is required for maintenance of H2BK120ub levels." (PMID 35954248, 2022). "The ability of Smurf2 to ubiquitinate and degrade RNF20, a RING-family E3 that controls histone H2B ubiquitination and genome stability, has been implicated in the tumor suppressive role of Smurf2 in a wide spectrum of tumors." (PMID 36612252, 2022).
tumor (continued). "Further in these preclinical models, metastases to the lung reflected the rate of tumour growth, with down-regulation of RNF20 resulting in an increase of lung metastases from basal-like cells only." (PMID 33233707, 2020). "The majority of reports in the literature describe RNF20 in a manner consistent with being classified as a tumour suppressor; however, some reports suggest a pro-oncogenic activity." (PMID 33233707, 2020). "We previously demonstrated that the E3 ubiquitin ligase SMURF2 plays a critical tumor suppressing role via its interaction with RNF20 (ring finger protein 20) in shaping chromatin landscape and preserving genomic stability." (PMID 33097595, 2020). "While we and others have uncovered potential opposing tumor-supportive or tumor-suppressive roles of H2Bub1 and its E3 ligases RNF20 and RNF40 in ER-positive and triple-negative BC11,12,16, the role of this epigenetic pathway in HER2+-BC is currently unclear." (PMID 33070155, 2020). "In this way, RNF20 works to selectively inhibit the transcription of pro-oncogenic genes located in condensed chromatin, supportive of a tumour suppressor function for this E3 ligase." (PMID 33233707, 2020). "For example, the ring finger protein 20 (RNF20) is involved in protein metabolism and ubiquitination; and its expression profiles were inconsistent and relatively low in the majority of tumor tissues compared to normal tissues." (PMID 33287876, 2020). "The RNF20/RNF20 (Bre1 complex) is documented as a tumor suppressor by upregulating a set of tumor suppressor genes and by contributing to genomic stability maintenance." (PMID 32000679, 2020). "On the other hand, this work highlights the tumor-suppressive role of RNF20 in ccRCC by inhibiting SREBP-1c." (PMID 29138263, 2017). "Consistent with potential tumor suppressor functions of RNF20/40 and H2Bub1 and their requirement for stem cell differentiation, we observed a widening of H3K4me3 peaks on RNF40-dependent lineage-specific genes during adipocyte differentiation." (PMID 28209164, 2017). "Tumour growth in athymic mice receiving tumours with RNF20, RNF40, Eg5 knockdown or Eg5 inhibition, was significantly suppressed, arguing for a role of the RNF20/40-Eg5 axis in breast carcinogenesis." (PMID 27557628, 2016). "The results indicated that tumour growth was significantly suppressed in athymic mice which had received tumours with either RNF20, RNF40, Eg5 knockdown or monastrol treatment." (PMID 27557628, 2016). "Other studies have shown that depletion of RNF20 inhibits both G1 arrest and apoptosis, but stimulates tumor advancement; its promotor is often hypermethylated in tumors." (PMID 22615993, 2012). "Human Bre1/RNF20 acts as a tumor suppressor by promoting transcription of tumor suppressor genes and repressing proto-oncogenes, underscoring the importance of both positive and negative gene regulation by H2B monoubiquitylation." (PMID 22408743, 2011). "Similarly, intravenous injection of RNF20 + /- A549 cells resulted in a significantly higher number of tumor nodules and an expanded metastatic area in the lungs compared to mice injected with control A549 cells." (PMID 40436847, 2025). "Our work demonstrates a previously unknown tumor-supportive role of RNF20 and RNF40 by regulating the peroxisome functions and thereby suppressing ferroptosis." (PMID 40597205, 2025). "However, the molecular mechanisms that link RNF20 to tumor development and progression remain insufficiently understood." (PMID 40436847, 2025). "For this reason, it has been hypothesized that H2Bub1 and RNF20 could display tumor-suppressive functions." (PMID 37770435, 2023).
tumor (continued). "For example, SMURF2 governs the chromatin organization, dynamics, and genome integrity by controlling the proteasomal degradation or the protein stability of its substrates including RNF20 or DNA topoisomerase IIa41,43, which in turn regulate tumorigenesis and tumor progression." (PMID 35017630, 2022). "Smurf2 is known to regulate RNF20, whose high expression strongly correlates with tumor formation." (PMID 36612252, 2022). "It is likely that additional tumour cell types will be discovered to increase the production of inflammatory cytokines in response to depletion of RNF20 and H2Bub1, contributing to a microenvironment conducive to initiating malignancy and/or driving tumorigenesis." (PMID 33233707, 2020). "In a study of 424 high-grade serous ovarian cancers, loss of RNF20 was only seen in ~6% of tumours and, perhaps surprisingly, did not correlate with loss of H2Bub1." (PMID 30669413, 2019). "Another way that RNF20 may function as a tumour suppressor is by stopping recruitment of the transcription elongation factor TFIIS to chromatin." (PMID 30669413, 2019). "A small number of studies have assessed RNF20 in primary tumours." (PMID 30669413, 2019). "In a recent study, RNF20 was demonstrated to have tumor suppressor activity in ccRCC." (PMID 29934362, 2018). "RNF20 has been suggested to act as a tumor suppressor in chronic inflammation-driven cancer." (PMID 29934362, 2018). "RNF20 has been suggested to act as tumor suppressor in chronic inflammation-driven cancer." (PMID 29934362, 2018). "Furthermore, RNF20 overexpression greatly reduced tumor growth and lipid storage in a xenograft mouse model." (PMID 29934362, 2018). "Thus, the authors have clearly demonstrated that RNF20 acts as a metabolic tumor suppressor by inhibiting SREBP-1c-mediated lipogenesis and cell cycle progression in ccRCC." (PMID 29138263, 2017). "Interestingly in group 4 where treatment was started after the development of tumor showed statistically significant upregulation of RNF20." (PMID 29066742, 2017). "Both RNF20 and Mex3c are considered as tumor suppressive genes in cancer." (PMID 29066742, 2017). "Importantly, in line with our cell culture-based assays, HIF1A silencing or inhibition of glucose uptake with the GLUT1 inhibitor WZB117 was sufficient to suppress the metabolic changes and reduce both the number of tumor nodules and the metastatic area in mice injected with RNF20 + /- A549 cells." (PMID 40436847, 2025). "Indirectly, RNF20 may function in a tumour suppressive capacity to obstruct the expression of oncogenes including MYC and FOS located in regions of compacted chromatin by interfering with recruitment of TFIIS that would usually function to relieve stalled RNA pol II." (PMID 33233707, 2020). "However, RNF20 had not been previously implicated in lipid metabolism-mediated tumor-suppressive function." (PMID 29138263, 2017). "To take possible reciprocal compensatory effects of the two E3 ligases into consideration, we combined RNF20 and RNF40 expression data (H2Bub1 score) better reflecting the activity of the H2Bub1 pathway in the tumor samples." (PMID 40597205, 2025). "Here, we find that the yeast ubiquitin ligase Bre1 and its human homolog RNF20, a tumor suppressor, function as recombination mediators, promoting Rad51 filament formation and subsequent reactions via multiple mechanisms independent of their ligase activities." (PMID 37230987, 2023). "Our study suggested that, like RNF43 and RNF20, RNF38 plays a tumor-suppressing role in NPC and is supposed to be a potential biomarker for predicting recurrence and metastasis according to our study." (PMID 35568845, 2022). "These subtle regulatory processes specifically affect genes that control genome stability and cell growth, supporting the inference that RNF20 and RNF40 act as tumor suppressors." (PMID 33199825, 2021).
tumor (continued). "Global levels of H2Bub1 and/or its E3 ligase complex members RNF20 and RNF40, have been investigated in numerous tumours using methods including immunohistochemistry and for RNF40 and/or RNF20, assessment of transcript levels and promoter hypermethylation." (PMID 33233707, 2020). "In basal-like TNBCs, there is an inverse relationship between USP44 and RNF20/RNF40 with USP44 being more highly expressed, concomitant with lower levels of H2Bub1 in these tumours." (PMID 33233707, 2020). "It has been reported that ring finger protein 20 (RNF20), a RING-finger containing E3 ubiquitin ligase, acts as a tumor suppressor by modulating histone monoubiquitination and epigenetic gene expression." (PMID 29138263, 2017). "As suggested by the previous results, tumor tissues expressed higher levels of RNF20 and RNF40 than normal and surrounding tissues." (PMID 40597205, 2025). "Ubiquitination (via SCF-FBXW7, RNF20, RNF139) or deacetylation (via SIRT1) promotes SREBP1 degradation, inhibiting fatty acid metabolism and maintaining lipid homeostasis. mTORC1 activation and SREBP1 acetylation enhance its stability and promote lipid metabolism, supporting tumor growth." (PMID 40370434, 2025). "Interestingly, the ability of HeLa and SiHa cells to form colonies under 2D conditions and tumor spheres under non-adherent 3D conditions was greatly reduced in the absence of RNF20 and RNF40." (PMID 40597205, 2025). "At present, it cannot be excluded that some tumour-suppressive or oncogenic functions of RNF20 and RNF40 might occur via non-histone substrates." (PMID 30669413, 2019). "Whether, and how, the RNF20/40 complex is functionally involved in mitosis, when it is supposed to be excluded from chromatin, is not clear; whether, and how, RNF20/40 E3 ligase plays a role in breast carcinogenesis is not understood." (PMID 27557628, 2016). "Interestingly, a positive correlation of RNF20 but not RNF40 to Ki67 was observed in the tumor cell cluster of SCC, pointing at a potential oncogenic function of this RNF20 and RNF40 driven H2Bub1." (PMID 40597205, 2025). "In addition to H2B, nonhistone substrates of RNF20/40 have been reported, although it cannot be concluded whether RNF20 or RNF40 act through ubiquitylation of such nonhistone proteins to exert their tumor-suppressive or oncogenic functions." (PMID 33199825, 2021).
cancer (29 papers, 2013 to 2026). A tumor composed of atypical neoplastic, often pleomorphic cells that invade other tissues. "Loss of RNF20/40 and H2B monoubiquitination (H2Bub1) is found in several cancers and is linked to an aggressive phenotype, and is also an indicator of poor prognosis." (PMID 29934362, 2018). "The implication of RNF20/H2BK120ub in the formation and/or stabilization of reversed replication forks might help explain why H2BK120ub levels in cancer are frequently downregulated, due to either loss of RNF20 or upregulation of the eraser USP22." (PMID 41145912, 2025). "Loss of RNF20 is associated with aggressive cancer phenotypes." (PMID 40436847, 2025). "In addition, depletion of RNF20 and H2BK120ub1 induces replication stress, adversely impacts DNA damage repair, and underlies chromosome instability, aberrant phenotypes that all contribute to cancer development and progression." (PMID 30781493, 2019). "Moreover, synthetic lethal strategies have the unique benefit of enabling targeting of loss-of-function alterations, which would be relevant for cancer types frequently exhibiting reduced expression of E3 ubiquitin ligases (e.g., RNF20 or RNF40) or DUBs (e.g., BAP1 or USP22)." (PMID 30781493, 2019). "Our results suggest that reduced RNF20 promoter activity resulting from NCVs constitutes another potential cancer mechanism." (PMID 36808133, 2023). "Through this modification, RNF20 reduces cell size by inactivating PPARγ in adipocytes and suppresses metastasis by regulating SREBP1c in cancer cells." (PMID 38068817, 2023). "As reviewed extensively in the literature, there is a tight connection between the activity of RNF20/40 and H2BK120ub and cancer development." (PMID 35954248, 2022). "For example, RNF20-depleted cancer cells are more sensitive to DNA damage induced by the PARP1 inhibitors olaparib or BMN673 than isogenic control cells." (PMID 30781493, 2019). "In this review, we summarized the current knowledge of RNF20 in chronic inflammation-driven cancers, DNA DSBs, and apoptosis, and its impact on chromatin structure beyond the single nucleosome level." (PMID 29934362, 2018). "The present review is designed to collate the existing literature, and critically analyze our current understanding and the recent advances in RNF20/40 mediated processes and their implication in cancer development." (PMID 29934362, 2018). "Ubiquitination of histone H2B is predominantly through E3 ligase RNF20 and it is found to be down-regulated in a majority of cancers." (PMID 29934362, 2018). "RNF20 and RNF40, which are implicated as tumor suppressor genes, are mutated or misregulated in various types of cancers." (PMID 29058668, 2017). "The human homologs of yeast BRE1, RNF20 and RNF40 are mutated and misregulated in different types of cancers." (PMID 29058668, 2017). "Since data-mining from TCGA database revealed that the expression of the histone H2B K monoubiquitin (H2Bub1) ligase RNF20 is dysregulated in cancer, we elucidated its effect on transcription and cancer progression." (PMID 29184082, 2017). "Mammalian Bre1 complexes (BRE1A/B and RNF20/40) in humans are important for maintenance of genomic integrity, which serves as a barrier against cancer formation." (PMID 29262668, 2017). "A subsequent study expanded this initial proof-of-principle to include five additional genes, which are frequently mutated in cancer (CDC4, MRE11A, RNF20, SMC1A, and SMC3) that are also selectively killed following FEN1 inhibition." (PMID 24202319, 2013). "Recent studies have offered new insights into how RNF20 regulates gene expression and developmental programs, and how misregulation of its activities leads to pathologies including developmental disorders and cancers." (PMID 42004469, 2026). "It will be intriguing to investigate whether the occurrence of this cancer is relevant to an altered RNF20-hRad51 interaction." (PMID 37230987, 2023).